EZH2 (enhancer of zeste 2 polycomb repressive complex 2 subunit)
Diseases named in the same sentence as EZH2 in open-access papers (continued):
Sharing a sentence is not in itself a finding about the gene and the disease.
melanoma (continued). "Therefore, it could be concluded that silenced CDKN1C accelerated the viability of melanoma cells and prevented melanoma cells from oxidative stress and apoptosis while EZH2 knockdown aided to improve these functions by upregulating the expression of CDKN1C." (PMID 32308561, 2020). "The increased expression of EZH2 in melanoma results in the hyper-activation of PRC2 with consequent tri-methylation of H3K27, silencing of CDKN2A and CDKN1A tumor suppressor genes, and is associated with thicker primary melanomas, aggressive metastatic behavior, and a poor prognosis." (PMID 31861757, 2019). "Here we report the regulation of expression of the NFIB transcription factor by BRN2 in melanoma cells, which in turn acts to increase cell migration and potentially invasion through the positive and negative regulation of the epigenetic regulator EZH2 and MITF respectively." (PMID 28119061, 2017). "Therefore, combination therapy with BRAF and EZH2 inhibitors may be particularly beneficial to patients with mucosal and unknown primary melanoma." (PMID 29202777, 2017). "Notably, in our cohort, the frequencies of EZH2 gain in mucosal (38.9%) and unknown primary melanoma (50%) are markedly higher than acral (21.9%), CSD (25.0%) and non-CSD melanoma (33.3%) subtypes." (PMID 29202777, 2017). "As these mutations do not enhance 2D-growth rate and the A375 melanoma cell line is a model that already grows rapidly in vivo, these surprising findings suggest that EZH2 GOF mutants likely impart properties to these cells that go beyond driving proliferation." (PMID 25671303, 2015). "Therefore blocking EZH2 activity may represent an effective strategy for preventing melanoma progression." (PMID 26304929, 2015). "Upon observing these striking morphological changes, we asked whether these changes were specific to the expression of EZH2 Y641 mutants (the only GOF mutants observed thus far in melanoma), or whether enhancement of H3K27me3 levels in general could also give rise to these phenotypes." (PMID 25671303, 2015). "Furthermore, as EZH2 mutations in melanoma are coincident with BRAF mutations they may serve to complement the function of BRAF (i.e. BRAF signaling drives cell division, whereas EZH2 signaling drives motility/migration)." (PMID 25671303, 2015). "Taken together, the data presented in this study strongly suggest that EZH2 GOF mutants contribute to melanoma progression by altering the way in which melanoma cells interface with their surrounding microenvironment and in this manner may confer a growth advantage to tumors bearing these mutations." (PMID 25671303, 2015). "Taken together, these data suggest that the EZH2 GOF mutations may not drive intrinsic melanoma cell proliferation (as do mutations in driver genes like BRAF), but rather function by shaping the interactions between melanoma cells and their microenvironment." (PMID 25671303, 2015). "To investigate whether the SSX2-mediated disintegration of BMI1 and EZH2 nuclear bodies in A375 melanoma cells influenced the repressive function of these proteins, we performed global gene expression profiling of A375 cells with and without ectopic SSX2 expression." (PMID 25249625, 2014). "We next determined whether EZH2 regulates miR-31 expression in melanoma cells." (PMID 22948084, 2012). "In melanoma, dysregulated lipid metabolism, driven by SCD1 overexpression, was shown to blunt the sensitivity to EZH2 inhibitors; the pharmacological inhibition of SCD1 successfully restored drug sensitivity in in vitro and in vivo models." (PMID 40573249, 2025). "In melanoma, the PRC2/EZH2 pathway mediates H3K27 hypermethylation, suppressing tsMHC-II expression and ultimately leading to immunotherapy resistance." (PMID 40495188, 2025).
melanoma (continued). "Consequently, the interaction of IκBζ with EZH2 and HDAC3 might be the most upstream event regulating IκBζ target genes in melanoma, whereas IκBζ-mediated gene activation derives from the additional presence of EZH2- and HDAC3-activated STAT3 and p65 at single gene promoters." (PMID 40562773, 2025). "Among downregulated genes after ICG-001 treatment, BIRC5, EZH2, E2F1, and other oncogenes related to melanoma were found." (PMID 41227355, 2025). "Based on these findings, we propose that constitutively expressed IκBζ in melanoma recruits HDAC3 and EZH2 to the gene loci of CXCL9, CXCL10, and CCL5, leading to inaccessible promoter regions of these genes." (PMID 40562773, 2025). "PRAME is a dominant repressor of retinoic acid (RA) signaling in melanoma and acute myeloid leukemia (AML) by interaction with the Enhancer of Zeste Homolog 2 (EZH2) and the RA receptor α (RARα) at RA response elements (RAREs)." (PMID 39550391, 2024). "Several studies have also observed that EZH2 plays a major role in repression of MHCI in head and neck, small cell lung cancer and melanoma, and MHCII in urothelial and AML cancers." (PMID 38265267, 2024). "EZH2 was reported to mediate PGC1α gene silencing, thereby increasing WNT5A expression and promoting migration and metastasis in melanoma." (PMID 38566211, 2024). "When we inhibited both BRAF and PLK1, we achieved an improved response of BRAFi-resistant melanoma cells, which was comparable to the combined inhibition of BRAF and EZH2." (PMID 36768289, 2023). "In summary, the combined inhibition of EZH2 and BRAF improves anti-cancer effects through enhanced cell-cycle arrest and the increased cell death of melanoma cells resistant to vemurafenib." (PMID 36768289, 2023). "IHC staining of UHRF1 expression in human melanomas showed that highly pigmented cells exhibiting increased UBE2L6 and decreased EZH2 also had low UHRF1 expression." (PMID 36906655, 2023). "We identified EZH2 as a master regulator of melanoma ITH and promoter of malignant behavior in melanoma cells." (PMID 36906655, 2023). "EZH2 inactivation reversed the resistance to anti-CTLA-4 and IL-2 immunotherapy and suppressed melanoma growth in mice models." (PMID 37427115, 2023). "It has been reported that constitutive activity of ERK1/2 triggers increased EZH2 expression and global H3K27me3 levels in BRAFV600 melanoma cells." (PMID 37325482, 2023). "Recently published research acknowledge EZH2 contribution to resistance to targeted therapy against BRAFV600 and MEK1/2 in melanoma." (PMID 37325482, 2023). "In this context, the histone methyltransferase EZH2, the effector subunit of the PRC2 polycomb complex, was shown to promote EMT-like melanoma cell plasticity." (PMID 35432344, 2022). "EZH2 inhibition can cooperate with anti-CTLA-4 and IL-2 immunotherapy to inhibit the growth of melanoma." (PMID 35907846, 2022). "The clinical use of EZH2 inhibitor, GSK503, controlled melanoma growth, restored tumor immunogenicity among these patients, and reversed resistance to tumor immunotherapy." (PMID 36230787, 2022). "EZH2 was also shown to be upregulated in response to TNFα induced by CTLA-4 blockade and IL2 agonist treatment in B16 and RIM3 melanoma models." (PMID 33859645, 2021). "Small molecule inhibitors against EZH2, a key effector of the BRN2 signaling, restored differentiation and impaired invasion of melanoma cells in vitro, and inhibited melanoma growth and metastasis in mouse models." (PMID 34604096, 2021). "Next, we analyzed the expression profiles of USP7, EZH2 and FOXO1 in human samples from histologically normal skin tissues in tumor-adjacent regions, nevus, malignant melanoma and metastatic melanoma." (PMID 33849069, 2021). "EZH2 was able to induce resistance to immunotherapy treatments anti-CTLA-4 and IL-2 in a melanoma mouse model and when inactivated, reversed this resistance." (PMID 34220955, 2021).
melanoma (continued). "Preclinical research has demonstrated that EZH2 inhibition synergizes with anti-CTLA-4 in mouse melanoma models, where EZH2 inhibition restored melanoma immunogenicity and antigen presentation." (PMID 34944799, 2021). "In melanoma cell lines, EZH2 is the only functional protein that binds to LINC-PINT in the nuclei, and LINC-PINT exerts an inhibitory effect on the pathogenesis of melanoma through enriching EZH2 to the promoter of its target genes." (PMID 34257531, 2021). "Histone lysine methyltransferase EZH2, responsible for H3K27 trimethylation, was also found to be dysregulated during the development of human melanomas." (PMID 34575678, 2021). "EZH2 is the catalytic subunit of the PRC2 complex and appears overexpressed in various tumors, including melanoma." (PMID 34575678, 2021). "In melanoma, specifically, NFIB-targeted upregulation of EZH2 led to the epigenetic silencing of MITF, promoting a highly invasive phenotype." (PMID 34922631, 2021). "The evidence provided by our study highlighted the involvement of lncRNA GAS5 in the translational suppression of EZH2 as well as the upregulation of CDKN1C, resulting in the promotion of melanoma cell apoptosis and oxidative stress." (PMID 32308561, 2020). "The correlation of lncRNA GAS5, EZH2, and CDKN1C with survival rate of melanoma patients was analyzed." (PMID 32308561, 2020). "Similar to EZH2, the histone methyltransferase EHMT2 drives melanoma growth and promotes an immunosuppressive microenvironment by activating the WNT signaling pathway." (PMID 33024276, 2020). "It was found that EZH2 presented significantly higher expression in melanoma tissues than in adjacent normal tissues, while the expression of CDKN1C in melanoma tissues was lower than that in adjacent normal tissues (p < 0.05)." (PMID 32308561, 2020). "This study went on to show that EZH2-mediated primary cilium disassembly enhances WNT/β-catenin signaling and promotes melanoma growth and metastasis." (PMID 33024276, 2020). "In vivo, the combination of GSK503, an Ezh2 inhibitor, with anti-CTLA-4 or IL-2 proved to be more efficient than monotherapies in the treatment of melanoma." (PMID 32867025, 2020). "Following after, RT-qPCR and western blot analysis were employed to examine the expression of EZH2 and CDKN1C in 6 pairs of melanoma tissues and adjacent normal tissues." (PMID 32308561, 2020). "Silencing lncRNA GAS5 accelerated the EZH2 expression as well as H3K27 trimethylation to suppress the CDKN1C transcription and oxidative stress in melanoma." (PMID 32308561, 2020). "Since overexpression of EZH2 accelerated H3K27 trimethylation leading to CDKN1C silencing and oxidative stress inhibition in melanoma." (PMID 32308561, 2020). "Here we show that the EMT-like transcriptional program of melanoma cells is indeed controlled by NFATc2 acting on c-Myc, FOXM1 and EZH2 and that NFATc2 regulates melanoma migratory and invasive activity in vitro, and tumor growth in vivo." (PMID 30710146, 2019). "The epigenetic regulators RNF2 and EZH2 promote the invasive, metastatic and EMT-like phenotype of melanoma cells." (PMID 30710146, 2019). "Others have shown that EZH2 inactivation can potentially synergize with checkpoint-based immunotherapy including anti-CTLA4 and PD-L1 in preclinical models of melanoma and ovarian cancer." (PMID 30692641, 2019). "FOXM1 is involved in the transcriptional control of the epigenetic regulator EZH2, the latter gene being also a regulator of the EMT program and of the invasive activity and metastatic ability of melanoma cells." (PMID 30710146, 2019). "Noteworthy, the enhancer of zeste homolog 2 (EZH2) is the core subunit of PRC2 endowed with methyltransferase activity, which is up-regulated in melanoma with respect to benign naevi." (PMID 31861757, 2019).
melanoma (continued). "NFATc2 silencing by shRNA or treatment of melanoma cells with inhibitors of NFATc2 (AM404), c-Myc (10058-F4), FOXM1 (Siomycin A) or EZH2 (GSK126) reduced significantly migratory activity, by wound healing assay, and invasive ability." (PMID 30710146, 2019). "Treatment with another EZH2 inhibitor, GSK503, in a melanoma mouse model, blocked tumor growth and metastasis formation." (PMID 30466474, 2018). "We were able to demonstrate that EZH2 is up-regulated following both BRN2 and NFIB stable overexpression in melanoma cells." (PMID 28119061, 2017). "Among the genes regulated by miR-31 are SRC, NIK, RAB27A and MET, whose products in turn, control transcription factors ultimately regulating EZH2 expression, which is known to be a key regulator of EMT in melanoma." (PMID 29112174, 2017). "In conclusion, our study identified EZH2 gain as a biomarker for selecting patients with BRAF V600E-mutated melanoma who may benefit from combination therapy with BRAF and EZH2 inhibitors, thus providing insights into a promising novel therapeutic strategy for the treatment of melanoma." (PMID 29202777, 2017). "Given the high coexistence rate (29%) of EZH2 gain and BRAF V600E mutation in our cohort, we for the first time evaluated the efficacy of combination therapy with EZH2 and BRAF inhibitors in melanoma cell lines and PDX mouse models." (PMID 29202777, 2017). "Ezh2S21A-, Ezh2- and GFP-Pmel-1 cell recipients of B16 melanoma had similar amounts of donor T cells in PB within 7d after transfer." (PMID 29242551, 2017). "Accordingly, the IGR1 melanoma cell line (lane 3) that contains an endogenous EZH2 Y641N mutation displayed a similar pattern of H3K27 modification compared to two WT-EZH2 skin cancer cell lines (A431 skin SCC (lane 1), A375 melanoma cells (lane 2))." (PMID 25671303, 2015). "In particular, EZH2, the catalytic subunit of the polycomb repressive complex 2 (PRC2), is overexpressed in many different types of cancers including melanoma, where it represses tumor suppressor genes." (PMID 26322273, 2015). "Inactivating mutations in SWI/SNF family member genes (ARID1A, ARID1B, ARID2, and SMARCA4) and in members of another chromatin-remodeling family referred to as the poly comb complex (EZH2, BMI1, and JARID1B/KDM5B) have been found altered in melanoma." (PMID 26322273, 2015). "Nevertheless melanoma cultures (KMKD) obtained from a patient before and after treatment with the BRAF inhibitor, vemurafenib showed a decrease in levels of EZH2 protein in the treated cells and a decrease in the GSK126 IC50 values." (PMID 26304929, 2015). "Little is known about the role of PcG proteins in melanoma, but BMI1 and EZH2 are also deregulated and correlate with disease progression." (PMID 25249625, 2014). "Several miR-214 targets have been characterized in various tumor types (ovarian cancer, cervical cancer and melanoma) including MEK3, JNK1, PTEN, Plexin-B1, Ezh2, and TFAP2C and so on." (PMID 22359598, 2012). "We validated the heterogeneity and aberration status within single biopsies by fluorescent in situ hybridization of four affected and transcriptionally up-regulated genes E2F8, ETV4, EZH2 and FAM84B in 11 melanoma cell lines." (PMID 21569352, 2011). "EZH2 inhibition has ability to induce a shift of H3K27 from trimethylation to acetylation, and EZH2 inhibitor (GSK‐126) showed to markedly reduce invasiveness and significantly suppress the tumor growth in NRASmut melanoma when combined with trametinib." (PMID 41492362, 2026). "Notably, inhibition of both EZH2 or HDAC3, can restore adaptive immunity in the TME and re-sensitize melanoma to immunotherapy." (PMID 40562773, 2025). "EZH2-targeted therapies have been successfully used to treat patients with follicular lymphoma and epithelioid sarcoma, but their clinical use in melanoma has not been described." (PMID 39984702, 2025).
melanoma (continued). "Ageing in fibroblasts induced Enhancer of zeste homolog 2 (EZH2) decline and increased Bone Morphogenetic Protein 2 (BMP2) secretion, these mechanisms induce slower-cycling, highly invasive and therapy-resistant melanomas." (PMID 41470117, 2025). "To this end, we have previously shown a similar synergistic effect with co-exposures to Tazemetostat (an EZH2 inhibitor) and SFN in A375 melanoma cells, thus further supporting SFN’s anticancer potential in combinatorial treatment protocols with various epi-drugs (e.g., Zebularine and Tazemetostat)." (PMID 40136320, 2025). "Additionally, overexpression of histone methyltransferase EZH2 can contribute to tumor-intrinsic ICI resistance by impairing antigen presentation, as well as by promoting the upregulation of PD-L1 expression on melanoma cells." (PMID 40554927, 2025). "Likewise, Tyr::CreERT2 - driven Ezh2 GOF, which results in canonical Wnt signal activation in the melanocyte lineage, promotes melanoma formation, whereas Plp1::CreERT2 -driven Ezh2 GOF in MPNSTs had no overt effect on the tumor phenotype." (PMID 41063628, 2025). "Similarly, compared to melanoma, strongly reduced expression of the PRC2 subunit Ezh2 was detected in MPNST, both in tumor cells and in the surrounding stroma." (PMID 41063628, 2025). "Based on these results, EZH2 and the PRC2 complex could serve as potential therapeutic targets for melanoma and other related tumors." (PMID 40491322, 2025). "Therefore, the expression of important proteins such as EZH2, ATRX, and LMNB1 can be maintained or adapted to keep and stabilize the increased proliferation rate of melanoma cells." (PMID 38431560, 2024). "In melanoma, H3K27me3 expression was negatively correlated with STING expression at the protein level and combining the EZH2 inhibitor GSK126 with STING agonists elevated MHC class I expression and chemokine production, restraining tumor growth and boosting CD8+ T cell infiltration." (PMID 39080807, 2024). "In contrast, fibroblasts, embryonic stem cells (ESC) and melanoma cells show enrichment of EZH2 or H3K27me3 at epithelial genes’ promoter regions but not at the mesenchymal ones." (PMID 37175580, 2023). "Of note, in a mouse model of lung and colon carcinomas immunotherapy has failed to induce EZH2 expression, suggesting a melanoma-specific role of PRC2 in controlling immune evasion." (PMID 37325482, 2023). "EZH2 knockout by CRISPR-Cas9 induced MITF in pigmented melanoma cell lines (28:B4:F3 and C006-M1), but not in non-pigmented SK-MEL-28 and A375 cells." (PMID 36906655, 2023). "Genetic or pharmacological depletion of EZH2, but not specific inhibition of its methyltransferase activity, inhibited melanoma cell tumorigenicity and invasion, indicating a critical methyltransferase-independent function for EZH2 in melanoma." (PMID 36906655, 2023). "As endogenously ubiquitinated EZH2 was undetectable by LC-MS in all tested melanoma cells (data not shown), we assessed Ube2l6-WT overexpressing B16-F10 cells, detecting Ezh2 ubiquitination at residue K376." (PMID 36906655, 2023). "The authors have speculated that EZH2 is responsible for the regulation of miR-129-5p/SOX4 axis, since EZH2-specific methyltransferase inhibitor tazemetostat triggered miR-129-5p diminution and reactivation of SOX4 in drug-resistant melanoma cell lines." (PMID 37325482, 2023). "Thus, the combination of BRAF inhibitors with inhibitors against EZH2 or against downstream targets of EZH2, such as PLK1, represent new therapeutic options for melanoma." (PMID 36768289, 2023). "In the melanoma B16-tumor-bearing mice model of transferred Ezh2fl/flCd4Cre Pmel CD8 + T cells, the tumor suppressor effect of these cells was significantly reduced when EZH2 was insufficient." (PMID 37626362, 2023).